MDM2 (MDM2 proto-oncogene)
Diseases named in the same sentence as MDM2 in open-access papers (continued):
Sharing a sentence is not in itself a finding about the gene and the disease.
tumor (continued). "Additionally, the differential expression of E2F1 and MDM2 proteins in response to the intervention indicates a shift towards a more favourable tumour microenvironment." (PMID 40111872, 2025). "Furthermore, it has been reported that MDM2 can promote tumor metabolic reprogramming by enhancing glucose uptake or directly activating pathways such as G6PD." (PMID 41203626, 2025). "Significantly, SP141 demonstrated the ability to inhibit MDM2 expression and effectively suppress tumor growth without causing any host toxicity at the effective dosage." (PMID 39802403, 2025). "The functional relationship between NF-κB and MDM2 may have significant implications for tumor cell survival." (PMID 41303785, 2025). "Similarly, single agents such as small-molecule inhibitors of Bcl-2 or MDM2 inhibited ACC tumor growth in vivo." (PMID 40371051, 2025). "AS1411-VH032 and homoAS1411 are novel tumor-targeting PROTACs that exploit AS1411 aptamer’s affinity for nucleolin to selectively degrade MDM2 in tumor cells, achieve effective tumor suppression with minimal toxicity, and offer a promising approach for precise and safe MDM2-targeted cancer therapy." (PMID 41170373, 2025). "Here, 8.7% of the screened tumor samples showed an MDM2 amplification." (PMID 41299419, 2025). "Furthermore, chromosome 12q amplicons containing CDK4 (12q14.1) and MDM2 (12q15) were detected both in the cfDNA and the tumor tissues, consistent with previous findings associating these co-amplifications with poor prognosis in patients with NB." (PMID 40386554, 2025). "Furthermore, we verified MDM2 expression using proteomics databases, patient-derived tumor and adjacent tissues, as well as tumor and normal cell lines." (PMID 40113745, 2025).
tumor (continued). "Immunohistochemical analysis of the resected specimen revealed focal positivity for CD34 and partial positivity for MDM2 in the tumor cells at the resection margin, whereas staining for CD31, AE1/AE3, SMA, desmin, and CDK4 was negative, indicating no specific line of differentiation." (PMID 41334114, 2025). "We found that IGF2BP1 and MDM2 protein levels correlated in cytokeratin-positive tumor cells." (PMID 41444249, 2025). "Elevated MDM2 expression can impair tumor cell killing by T cells, thus promoting immune evasion." (PMID 40521302, 2025). "Additionally, our model demonstrated lower predictive power for tumours on the trunk (model 3: AUC 0.929), suggesting that for larger lesions in this region, MDM2 amplification analysis should still be performed as standard practice." (PMID 40564858, 2025). "Further studies showed that MDM2 knockout led to reduced cell proliferation and tumor growth." (PMID 40428391, 2025). "Therefore, the present study aimed to prepare a ternary complex containing MDM2-siRNA (MDM2-siRNA complex) and investigate its anti-tumor effect in peritoneal dissemination model mice." (PMID 41009451, 2025).
tumor (continued). "Later, researchers also found that targeting MDM2 has the effect of enhancing tumor immunotherapy." (PMID 38577591, 2024). "USP15 regulates the stability and activity of MDM2 in T cells and tumor cells." (PMID 39263534, 2024). "MDM2-overexpressed tumor cells may elicit adaptive immune-mediated T cell killing, whereby the use of tumor antigenic peptides to create tumor vaccines may be efficacious." (PMID 39263534, 2024). "Additionally, our patient’s tumor harbored several other genetic alterations, including a frameshift mutation in PTEN and copy number amplification of the MDM2 and FGF4 genes." (PMID 39590120, 2024). "Furthermore, we demonstrate the combination activity of VP-16 and RG7112, an MDM2 inhibitor, in the xenograft tumor model and in situ lung cancer mouse model." (PMID 38263255, 2024). "Moreover, in vivo, FPFT-2216 elicited a potent tumor regression effect in combination with the MDM2 inhibitor siremadlin and enhanced the antitumor activity of the anti-human CD20 antibody rituximab." (PMID 38265263, 2024). "Likewise, the reduced expression of MDM2 in HCC is a predictor of better survival in patients after tumor resection." (PMID 38741108, 2024). "However, PD-L1 can also be used as a marker of immunotherapy efficacy, and the use of MDM2 inhibitors to increase PD-L1 expression in tumor cells or the TME in animal experiments with improved immunotherapy efficacy is a seemingly attractive therapy." (PMID 39263534, 2024). "On the contrary, the CCK8 and clone formation assays indicated that AGPS overexpression inhibited tumor cell growth, and concomitant overexpression of MDM2 resulted in significantly higher PCa cell activity as compared to the experimental group overexpressing AGPS alone." (PMID 38200609, 2024). "In view of these reports and our findings in the present study, an enhancement in MDM2 protein stability by RPS4X could potentially lead to tumor progression and poor prognosis." (PMID 39199272, 2024). "overexpressed NTN1 and found that MDM2 expression levels increased, Cyclin D1 expression declined, which then induced enhanced cellular invasiveness in vivo and in vitro, and provided adhesion substrates for tumour cells." (PMID 38546656, 2024). "It has been reported that more than 17% of human tumor exhibited MDM2 gene amplification." (PMID 38421457, 2024).
tumor (continued). "Until that time, the CXCL12/CXCR4/MDM2/MDMX axis in tumor metastasis is speculative since only the role of in vitro cell migration has been assessed in the current manuscript." (PMID 39766093, 2024). "Moreover, MDM2 is vitally involved in modifying the tumor immune microenvironment (TIME) as well as in influencing immune cells, eventually facilitating immune evasion and tolerance." (PMID 38281981, 2024). "Similarly, YX-02-030, a PROTAC molecule targeting the MDM2 protein degradation, exhibits enhanced anti-tumor activity compared to specific MDM2 inhibitors." (PMID 38699644, 2024). "Tumor growth, metastasis, and immune escape increase when MDM2 is overexpressed or amplified." (PMID 39263534, 2024). "Several preclinical studies have shown that MDM2 is involved in tumor immune evasion." (PMID 39263534, 2024). "By immunohistochemistry, the tumor cells showed strong reactivity for MDM2." (PMID 39165424, 2024). "The primary aim of this targeted review was to provide both a qualitative synthesis of the evidence on the incidence and prevalence of BTC and its subtypes in different geographic regions, as well as to clarify knowledge on the frequency of MDM2 amplification in BTC tumours." (PMID 39302603, 2024). "Additionally, the MDM2 inhibitor Nutlin-3 was found to enhance antitumor responses of MDM2-specific T cells by upregulating human leukocyte antigen (HLA) class II expression on tumor cells with the aid of CD4 + T cells." (PMID 38281981, 2024). "However, in other studies, MDM2 has been found to promote immune evasion, which is possibly due to the tumor heterogeneity triggered by differences in individuals, cancer types, epigenetic inheritance, signaling pathways, and other factors." (PMID 39263534, 2024). "Inhibitors of MDM2, such as Nutlin-3, exhibit anti-tumor effects." (PMID 39223632, 2024). "Overall, these data point out a challenging condition with a very aggressive outcome, while MDM2/MDM2 assays might help the understanding of these tumours to a better choice of therapy." (PMID 38732333, 2024). "Notably, PYGO2, UBQLN4, and ANXA1 have been associated with responsiveness to tumor immune checkpoint blockade (ICB) therapy, while B4GAL and MDM2 are implicated in regulating CD8 + T cell function and tumor growth." (PMID 38834869, 2024). "Notably, MDM2 is a tumor-specific MHC-II (TsMHC-II), and several studies on various cancer types have found an association between TsMHC-II and a good prognosis." (PMID 39263534, 2024). "Genomic analysis in terms of MDM2 amplification/co-amplification in intimal type might help MDM2 immunohistochemistry results since 10% to 20% of these tumours are MDM2-negative." (PMID 38732333, 2024). "Furthermore, MDM2 can alter the tumour immune microenvironment, helping cancer cells evade immune detection and destruction, complicating the immune system's ability to combat cancer." (PMID 39498386, 2024). "The concordant changes in protein expression results with the values detected at the gene expression can be observed in all the evaluated parameters of integrin αV, brevican, CSPG-5, versican, integrin β-5, and CD44 and only in tumor staining in the case of MDM2, MMP2, and FLT-4." (PMID 39595920, 2024).
tumor (continued). "Similarly, recent research findings suggest that MDM2 overexpression promotes angiogenesis by inducing a balance in cytokine expression that is conducive to an angiogenic state, ultimately enhancing tumor cell migration and invasiveness." (PMID 38281981, 2024). "The combined effect of increased MHC I and RAE-1 expression suggests that Sulanemadlin and small molecule MDM2 inhibitors may enhance tumor cell immunogenicity in vivo." (PMID 38784022, 2024). "However, it is known that tumor cells respond differently to MDM2 signaling depending on their basal levels of NF-κB." (PMID 38784022, 2024). "However, in vivo experimentation has shown that the development of self-tolerance to tumor cells expressing MDM2 can occur among MDM2-specific CTLs." (PMID 38281981, 2024). "Furthermore, both USP7 and MDM2 mRNAs were highly expressed in tumour tissues, but DICER mRNA was highly expressed in normal tissues." (PMID 37867415, 2024). "The expression levels of MDM4 and MDM2 were higher in the tumor samples than in the normal samples." (PMID 39345743, 2024). "Furthermore, this tumor harbored amplification of MDM2, as revealed by fluorescence in situ hybridization testing (FISH) and next-generation DNA sequencing (NGS)." (PMID 38549925, 2024). "Therefore, MDM2-based regulation of tumor cell-intrinsic immunoregulation and the immune microenvironment has attracted increasing research attention." (PMID 39263534, 2024). "Murine double minute 2 (MDM2), another target of miR-3174, is a tumor-promoting gene." (PMID 37298284, 2023). "In the present case, co-copy number amplification of CDK4 and MDM2 may have cooperatively upregulated cell cycle and promoted tumor progression." (PMID 38012788, 2023). "Importantly, MDM2 was more frequently overproduced in metastatic and recurrent tumours compared to primary tumours." (PMID 37185737, 2023). "In other words, analogous to CDKN2A/B HD, CDK4 and MDM2 co-amplification might accelerate tumor progression and may induce a malignant phenotype." (PMID 38012788, 2023).